UGT1A1 (UDP glucuronosyltransferase family 1 member A1)
Diseases named in the same sentence as UGT1A1 in open-access papers (continued):
Sharing a sentence is not in itself a finding about the gene and the disease.
Hyperbilirubinemia (continued). "This is not surprising, since Gilbert syndrome, which is caused by TA7 allele insertion in the UGT1A1 promoter region and characterized with mild unconjugated hyperbilirubinemia, is associated with low prevalence as well as incidence of ischemic heart disease." (PMID 36358491, 2022). "Our previous studies had confirmed the strong association between the common coding variant G211A (UGT1A1*6) and severe hyperbilirubinemia in Han population of southern China." (PMID 36520959, 2022). "The combined UGT1A1*28 and *6 polymorphism is a strong risk factor for the development of severe hyperbilirubinemia in Thai neonates." (PMID 35501760, 2022). "A large number of studies have shown that uridine diphosphate (UDP)-glucuronosyltransferase 1A1 (UGT1A1) gene mutations are one of the main genetic causes of hereditary unconjugated hyperbilirubinemia." (PMID 35415244, 2022). "With the development of modern molecular biology and gene cloning technologies, gene therapy has great potential for treating severe hyperbilirubinemia due to a severe deficiency or complete loss of UGT1A1 enzyme activity." (PMID 35415244, 2022). "The complete deficiency of UGT1A1 enzymatic activity causes hyperbilirubinemia in the Gunn rat, making it the first hyperbilirubinemia animal model to mimic the CNS-I syndrome." (PMID 36078055, 2022). "In an experimental model, mice with hyperbilirubinemia in Gilbert's mutation UGT1A1*28 were resistant against high fat diet-induced adiposity, hyperinsulinemia, and hepatic steatosis." (PMID 35436955, 2022). "Our results demonstrated that all Thai neonates carrying the homozygous variant in UGT1A1*6 were significantly classified into the hyperbilirubinemia group." (PMID 35501760, 2022). "Associations of UGT1A1 variants and neonate hyperbilirubinemia under different inheritage model assumptions: Logistic regression analysis." (PMID 36520959, 2022). "Serum bilirubin concentrations, the prevalence of benign hyperbilirubinemia > 17 μmol/L (1 mg/dL, a phenotypic sign of GS), and a variant of the UGT1A1 gene promoter responsible for GS manifestation in Caucasians (rs81753472) were evaluated in study subjects." (PMID 35759151, 2022). "UGT1A1*6 variants contribute to disordered bilirubin that results the clinical phenotype of neonatal hyperbilirubinemia." (PMID 36128448, 2022). "For example, mutations of the UGT1A1 gene are linked to an increased risk of neonatal hyperbilirubinemia in Asian populations, as compared with white populations." (PMID 35356100, 2022). "The combined UGT1A1*28 and *6 polymorphism was a strong risk factor for hyperbilirubinemia in Thai neonates." (PMID 35501760, 2022). "In humans, there is a benign condition of inheritable hyperbilirubinemia (total bilirubin levels ≥ 17.1 μmol/L) caused by deficiencies of UGT1A1, called Gilbert’s syndrome (GS), affecting 5–10% of Caucasians." (PMID 35436955, 2022). "It is noteworthy that the increased risk of hyperbilirubinemia is caused by nilotinib, because it inhibits human uridine diphosphate-glucuronosyltransferase (UGT1A1) activity." (PMID 36294746, 2022). "One should also underline that the reduction of UGT1A1 activity would result in the disturbance of bilirubin natural metabolism in patients and would lead to hyperbilirubinemia." (PMID 33915981, 2021). "A limited number of studies were identified that assessed the impact of UGT1A1 variants on pazopanib or nilotinib-induced hyperbilirubinemia." (PMID 33805415, 2021). "This is the first study to demonstrate an association of hyperbilirubinemia/UGT1A1 impairment with organ masses." (PMID 33762933, 2021). "In this study, we also observed that co-expression of TA6 allele, but not TA7, with the exon mutation (rs8175347-rs4148323-rs34946978: TA6AC/TA6GT) in UGT1A1 gene was associated with increased bilirubin levels and neonatal hyperbilirubinemia risk." (PMID 34074250, 2021).
Hyperbilirubinemia (continued). "Our study demonstrated that UGT1A1 variants contributed to the increased bilirubin level and risk of developing hazardous neonatal hyperbilirubinemia in ABO HDNs." (PMID 34074250, 2021). "Conjugation (or glucuronidation) by UGT1A1 is essential for the elimination of bilirubin, and thus, a polymorphism in the UGT1A gene results in the accumulation of UCB in the serum (hyperbilirubinemia)." (PMID 34771701, 2021). "TATA mutation of UGT1A1 promoter coupled with G6PD deficiency was indicated as an important factor for neonatal hyperbilirubinemia in Nigeria." (PMID 34895177, 2021). "Crigler-Najjar syndrome (CNs), severe unconjugated hyperbilirubinemia, results from the deficiency of UGT1A1, the enzyme that catalyzes the conjugation of unconjugated bilirubin (UCB) with UDP-glucuronic-acid." (PMID 33891666, 2021). "Univariate logistic regression analysis showed that the UGT1A1*28 allele was significantly associated with severe hyperbilirubinemia, in a recessive inheritance model (OR = 8.33, p = 0.023, 95% CI: 1.33–52.03)." (PMID 34093191, 2021). "The same situation was observed with ATV where we demonstrated a statistical significant association between moderate and severe hyperbilirubinemia (total bilirubin level >1.9 mg/dl) and UGT1A1*28." (PMID 34093191, 2021). "This study presents the first comprehensive evaluation of body composition and mitochondrial function in an animal model of UGT1A1 mutation and unconjugated hyperbilirubinemia." (PMID 33762933, 2021). "Neonatal hyperbilirubinemia is caused by a limited capacity to metabolize bilirubin mainly due to delayed expression of UGT1A1." (PMID 34045606, 2021). "Pazopanib impedes the metabolism of bilirubin through direct inhibition of UGT1A1, and when prescribed to those harboring UGT1A1 genetic variants, the incidence of hyperbilirubinemia is proposed to be higher." (PMID 33805415, 2021). "For the published studies assessing the impact of UGT1A1 on belinostat toxicities, evidence was supportive of UGT1A1 PMs having an increased risk of hyperbilirubinemia." (PMID 33805415, 2021). "UGT1A1 variant in coding region is actively involved in the pathogenesis of ABO hemolysis related neonatal hyperbilirubinemia." (PMID 34074250, 2021). "Those with UGT1A1 polymorphisms prescribed nilotinib are proposed to have an increased risk of hyperbilirubinemia." (PMID 33805415, 2021). "Although only the heterozygous c.1091C > T variant was identified in the present study, it has shown to increase bilirubin levels and hyperbilirubinemia risk in ABO HDNs in combination with other variant alleles of UGT1A1 genes." (PMID 34074250, 2021). "Among more than 100 mutation types of UGT1A1, the G to A variation at the nucleotide 211 of the UGT1A1 (UGT1A1*6, c.211G > A, p.Arg71Gly, rs4148323) is the most frequent mutation in the Asian cohort, contributes to hyperbilirubinemia in Asian neonates." (PMID 34895177, 2021). "A total of 5 studies were found that investigated the influence of UGT1A1 polymorphisms on hyperbilirubinemia in patients treated with pazopanib." (PMID 33805415, 2021). "Reduced activity of UGT1A1 caused by mutations in the UGT1A1 gene results in progressive unconjugated hyperbilirubinemia, a rare autosomal recessive disease CN1, and patients with CN1 do eventually require a liver transplant for survival." (PMID 32630053, 2020). "In GS, reduced (20–30% of wild-type) glucuronidation activity of UGT1A1 causes lifelong mild unconjugated hyperbilirubinemia." (PMID 32796590, 2020). "For instance, patients carrying UGT1A1*28 (rs8175347) treated with sorafenib undergo higher hepatic exposure to this drug and hence an increased risk of acute hyperbilirubinemia, which often leads to treatment interruption." (PMID 32585893, 2020).
Hyperbilirubinemia (continued). "Deletion of the Ugt1 locus from mice leads to neonatal lethality, whereas Gunn rats carrying a spontaneous truncating mutation in the Ugt1a1 gene exhibit unconjugated hyperbilirubinemia and jaundice but are otherwise viable." (PMID 32796590, 2020). "Several pharmaceutical compounds are known to cause hyperbilirubinemia via inhibition of OATP1Bs, UGT1A1, or BSEP." (PMID 32796590, 2020). "Currently, there is no ideal medication can be used for the prevention and treatment of hyperbilirubinaemia or other UGT1A1 deficiency associated disorders in clinical setting." (PMID 33628187, 2020). "We had previously shown that mice with the Gilbert’s mutation UGT1A1*28 and hyperbilirubinemia were resistant to high-fat diet-induced hepatic steatosis by inhibiting de novo lipogenesis and activation of β-oxidation." (PMID 33390979, 2020). "Nearly 60% of transcriptional activity is reduced at UGT1A1 * 60, so the increased risk of hyperbilirubinemia is inextricably linked to its presence." (PMID 33158427, 2020). "We have previously shown that mice with the human UGT1A1*28 Gilbert’s polymorphism and hyperbilirubinemia on a high-fat diet had significantly reduced hepatic fat accumulation and increased liver glycogen content compared to controls." (PMID 32961782, 2020). "Fourteen genetic variants in the UGT1A1 or SLCO1B gene were genotyped through sequencing in 148 adults with unconjugated hyperbilirubinemia and 158 healthy controls." (PMID 31737051, 2019). "Five included trials compared the risk of hyperbilirubinemia between HIV-positive patients with a UGT1A1*28 allele and those with a wild-type allele." (PMID 30962262, 2019). "Gilbert’s syndrome is a genetic disorder that is caused by mutations in UGT1A1 genes, UGT1A1*28 and to a lesser extent UGT1A1*6, and is characterized by hyperbilirubinemia." (PMID 30377777, 2019). "Polymorphisms in the promoter and coding region of the UGT1A1 gene often underline Gilbert Syndrome (GS), a mild unconjugated hyperbilirubinemia condition." (PMID 31737051, 2019). "In total, our study broadens the knowledge concerning traits associated with UGT1A1 variations and helps profile genotype–phenotype correlations in hyperbilirubinemia patients." (PMID 31467903, 2019). "Four included trials compared the risk of hyperbilirubinemia between HIV-positive patients with a UGT1A1*1/*28 genotype and those with a wild-type allele." (PMID 30962262, 2019). "In conclusion, the presence of the UGT1A1*28 allele with ATV use increases the risk of developing severe hyperbilirubinemia." (PMID 30962262, 2019). "To date, >130 variants in both the regulatory and coding regions of UGT1A1 have been identified in hereditary hyperbilirubinemia patients, with variations identified in CN-I, CN-II, and GS reducing UGT1A1 enzyme activity to 0%, 10%, and 30%, respectively." (PMID 31467903, 2019). "Four analyses suggested an increased risk of hyperbilirubinemia in HIV-positive patients with the UGT1A1*28 allele as compared with those with a wild-type allele (OR = 4.34, 95%CI = 2.55–7.39; P<0.00001)." (PMID 30962262, 2019). "Crigler-Najjar syndrome (CNs) presents as unconjugated hyperbilirubinemia, as a result of UGT1A1 deficiency, and can be categorized in a severe (type I) and mild (type II) phenotype." (PMID 31142299, 2019). "ATV causes hyperbilirubinemia due to inhibition of the enzyme uridine diphosphate glucuronosyltransferase 1A1 (UGT1A1), which is involved in the bilirubin conjugation." (PMID 30962262, 2019). "Overall analyses suggested an increased risk of hyperbilirubinemia in HIV-positive patients with a UGT1A1*28/*28 genotype as compared with those with a wild-type genotype (OR = 10.07, 95%CI = 4.39–23.10; P<0.00001)." (PMID 30962262, 2019). "Our findings broaden the knowledge concerning traits associated with UGT1A1 variants and help profile genotype–phenotype correlations in hyperbilirubinemia patients." (PMID 31467903, 2019).
Hyperbilirubinemia (continued). "Previous studies reported that premature birth is associated with a defective UGT1A1 protein causing immaturity of the conjugating enzyme, therefore increasing the risk of severe hyperbilirubinemia." (PMID 31440488, 2019). "UGT1A1 is not only involved in neonatal hyperbilirubinemia, but certain variants are also important in drug delivery." (PMID 31440488, 2019). "The present investigation has confirmed and expanded on our previous findings on the association of UGT1A1*60 and UGT1A1*6 with neonatal hyperbilirubinemia in Indonesia." (PMID 31440488, 2019). "Based on multivariate logistic regression results, four SNPs of UGT1A1, which increased the risk of hyperbilirubinemia, formed 5 common haplotypes with frequencies > 1%." (PMID 31737051, 2019). "Two articles provided incomplete data concerning the association between UGT1A1*28 mutation and incidence of hyperbilirubinemia." (PMID 30962262, 2019). "On the other hand, an abnormality or deficiency in UGT1A1 in vivo is strongly correlated with certain diseases (Gilbert syndrome, Crigler-Najjar syndrome, and hyperbilirubinemia), the toxicity of drugs, and the precise therapeutic profile." (PMID 31150474, 2019). "A significantly increased risk of hyperbilirubinemia was observed in HIV-positive patients receiving ATV with the UGT1A1*1/*28 or UGT1A1*28/*28 genotype, and the risk was higher with the UGT1A1*28/*28 genotype than with the UGT1A1*1/*28 genotype." (PMID 30962262, 2019). "Four included trials compared the risk of unconjugated hyperbilirubinemia between HIV-positive patients with a UGT1A1*28/*28 genotype and those with a wild-type genotype." (PMID 30962262, 2019). "The risk of hyperbilirubinemia is dependent on ATV plasma concentrations as well as genetic factors influencing UGT1A1 function." (PMID 30962262, 2019). "In this study, we identified UGT1A1 variants in 60 patients with unconjugated hyperbilirubinemias, including 55 GS patients, three CN-II patients, and two Intermediate patients, based on their bilirubin levels." (PMID 31467903, 2019). "Genetic deficiency of UGT1A1 or MRP2 is associated with various forms of hyperbilirubinemia such as Crigler-Najjar, Gilbert and Dubin-Johnson syndromes 12,13." (PMID 31410205, 2019). "Hereditary unconjugated hyperbilirubinemia, including CN-I, CN-II, and GS, is, respectively, caused by mutations in UGT1A1 (OMIM∗191740), which is a member of the UGT1 superfamily and located on chromosome (2q37)." (PMID 31467903, 2019). "Overall analyses suggested an increased risk of hyperbilirubinemia in HIV-positive patients with a UGT1A1*1/*28 genotype as compared with those with a wild-type allele (OR = 3.50, 95%CI = 1.35–9.08; P=0.01)." (PMID 30962262, 2019). "The primary finding of the present study is that HIV-positive patients carrying UGT1A1*28 allele(s) including UGT1A1*1/*28 and UGT1A1*28/*28 are at an increased risk of hyperbilirubinemia than those carrying the UGT1A1*1/*1 allele." (PMID 30962262, 2019). "Whereas, the presence of UGT1A1*6 is known to be a risk factor for mild adult hyperbilirubinemia (GS) in Caucasian and East Asian populations, the prevalence of this SNP is low in the Southeast Asian population." (PMID 31440488, 2019). "Allelic differences in UGT1A1 in a Chinese population with hyperbilirubinemia are expected; therefore, the present study investigated the allelic frequency and distribution of UGT1A1 variants in southeastern Chinese patients with hyperbilirubinemia." (PMID 31467903, 2019). "Overall, analyses suggested an increased risk of hyperbilirubinemia in HIV-positive patients with a UGT1A1*28/*28 genotype as compared with those with a UGT1A1*1/*28 or UGT1A1*1/*1 genotype (OR = 5.91, 95%CI = 3.30–10.58; P<0.00001)." (PMID 30962262, 2019). "The spectrum of UDP-glucuronyl transferase A1 (UGT1A1) variants in hereditary unconjugated hyperbilirubinemia varies markedly between different ethnic populations." (PMID 31467903, 2019).
Hyperbilirubinemia (continued). "Patients carrying the UGT1A1*28/*6 gene polymorphism who had indirect hyperbilirubinemia while recovering from chronic liver diseases can present with a pattern similar to that seen for GS patients." (PMID 29386646, 2018). "Gilbert’s syndrome is a condition of mild hyperbilirubinemia (serum bilirubin levels of 1 to 5 mg/dL) and is caused by a mutation in the gene promoter for UGT1A1, with marked impairment of bilirubin conjugation and excretion." (PMID 30597982, 2018). "In conclusion, UGT1A1*28/*6 gene polymorphisms are correlated with the development of unconjugated hyperbilirubinemia in clinical GS and post-hepatitis hyperbilirubinemia." (PMID 29386646, 2018). "UGT1A1*28/*6 gene polymorphisms are correlated with the development of unconjugated hyperbilirubinemia in both clinical GS and post-hepatitis hyperbilirubinemia." (PMID 29386646, 2018). "Our study investigated the characteristics of UGT1A1 polymorphisms in Chinese patients with post-hepatitis hyperbilirubinemia and Gilbert’s syndrome (GS)." (PMID 29386646, 2018). "In high risk hyperbilirubinemia group, there is more incidence of wild type exon 1 with heterozygous UGT1A1*60 (GG/TG; 10–0%) and heterozygous UGT1A1*6 with heterozygous UGT1A1*60 (GA/TG; 3.3–0%) compared to low risk hyperbilirubinemia." (PMID 29534743, 2018). "In Bengkulu neonates, both mutation UGT1A1*6 and UGT1A1*60 was found in hyperbilirubinemic neonates but they do not act as individual risk factors to the severity of the neonatal hyperbilirubinemia." (PMID 29534743, 2018). "We found heterozygous UGT1A1*60 4 times (13.3%) and homozygous 26 times (86.7%) in the hyperbilirubinemia group, with an identical allele frequency of 0.935 in hyperbilirubinemia and 1 in control group." (PMID 29534743, 2018). "The UGT1A1*6 (c211G > A) mutation in exon 1, which causes decreased enzyme activity, was found to be associated with neonatal hyperbilirubinemia in Asian populations, as well as one of the most prevalent polymorphism in East Asian population." (PMID 29534743, 2018). "The UGT1A1*60 (c-3279T > G) mutation in promoter region was found to be a frequent mutation in the Egyptian neonates with neonatal hyperbilirubinemia." (PMID 29534743, 2018). "The gene polymorphisms of UGT1A1*28/*6 in patients who had indirect hyperbilirubinemia during the recovery period from chronic liver diseases presented with a similar pattern to that of GS patients but differed from that for chronic active hepatitis patients." (PMID 29386646, 2018). "Inherited unconjugated hyperbilirubinemia is caused by variants in the gene UGT1A1 leading to Gilbert’s syndrome and Crigler-Najjar syndrome types I and II." (PMID 30285761, 2018). "Currently, the associations of the TATA box in the promoter region of the UGT1A1 gene with the risk of neonatal hyperbilirubinemia are reported to vary greatly in populations and regions." (PMID 30298137, 2018). "A study on Malaysian neonates concluded that the allele frequency of UGT1A1*60 was significantly higher in hyperbilirubinemia neonates when compared to controls." (PMID 29534743, 2018). "First, we wanted to evaluate vector-associated toxicity within the setting of any pathology associated with the defect in UGT1A1, the associated hyperbilirubinemia, and its sequelae." (PMID 30112420, 2018). "In this study, we investigated the correlation between polymorphisms in the gene encoding UDP-glucuronosyltransferase, UGT1A1, and the development of unconjugated hyperbilirubinemia in clinical GS and post-hepatitis hyperbilirubinemia." (PMID 29386646, 2018). "It has been known also that UGT1A1 variants were underlying cause of prolonged unconjugated hyperbilirubinemia associated with breast milk in Japanese population." (PMID 29607327, 2018). "The allele frequency of UGT1A1*60 in Egyptian neonates was 49.2% for the hyperbilirubinemia group and 25.6% for the control group, while in East Asian neonates the frequency is lower ranging from 25% to 27%." (PMID 29534743, 2018).